RNU6-961P (RNA, U6 small nuclear 961, pseudogene)
Gene: Small nuclear RNA gene on chromosome 2 (20,175,805 to 20,175,909, forward strand). Ensembl gene ENSG00000200763.
Homologues: Orthologues: chimpanzee U6 (100% identical), macaque U6 (94% identical), pig U6 (75% identical). Paralogues in human: RNU6-211P (93% identical), RNU6-1152P (91% identical), RNU6-15P (91% identical), RNU6-20P (91% identical), RNU6-310P (91% identical), RNU6-35P (91% identical), RNU6-812P (91% identical), RNU6-940P (91% identical), RNU6-1145P (90% identical), RNU6-1316P (90% identical), RNU6-16P (90% identical), RNU6-188P (90% identical), and 1289 more.